RHOA (ras homolog family member A)
Diseases named in the same sentence as RHOA in open-access papers (continued):
Sharing a sentence is not in itself a finding about the gene and the disease.
liver fibrosis (continued). "In conclusion, our results indicate that NOX4/ROS and RhoA/ROCK1, which may interact, play an important role in the development of liver fibrosis." (PMID 32496208, 2020). "We attempted to identify changes in the intestinal microbiota based on high-throughput sequencing techniques using a mouse model of liver fibrosis and to determine whether these changes have a correlation with the profibrotic factors NOX4 and RhoA." (PMID 32083022, 2020). "UA can reverse liver fibrosis by inhibiting the NOX4/ROS and RhoA/ROCK1 signalling pathways, which may interact with each other." (PMID 32496208, 2020). "The mechanism of interaction between NOX4/ROS and RhoA/ROCK in liver fibrosis has not been determined, although both NOX4/ROS and RhoA/ROCK are involved in regulating HSC activation in association with the progression of fibrotic disease." (PMID 32496208, 2020). "In conclusion, our study found that there is a disorder in the intestinal microbiota during liver fibrosis, and this disorder may be related to profibrotic factors NOX4 and RhoA." (PMID 32083022, 2020). "The interaction between NOX4/ROS and RhoA/ROCK1 in liver fibrosis is not yet clear." (PMID 32496208, 2020). "Therefore, we speculate whether the disorder of intestinal microbiota in liver fibrosis is related to NOX4 and RhoA." (PMID 32083022, 2020). "We also established a mouse liver fibrosis model by intraperitoneally injecting mice with CCl4 for 6 weeks, and in vivo experiments further verified the effect of carvedilol on the AT1R-mediated RhoA/Rho-kinase pathway, which might affect cell contraction and fibrogenesis." (PMID 31828132, 2019).
bladder cancer (23 papers, 2011 to 2025). "Overexpression of RHOA, a member of the rho family of small guanosine triphosphatases that regulates cell attachment, motility, and shape, has been associated with bladder cancer cell proliferation and metastasis." (PMID 41342186, 2025). "Ras-induced RhOA and NF-kappaB activation were implicated in promoting the invasion and migration of bladder cancer cells." (PMID 41342186, 2025). "Our teammates did a research and found that circUBE2K could mediate RhoA associated bladder cancer phenotype via regulation of miR-516b-5p/ARHGAP5 axis." (PMID 36840946, 2023). "Thus, even a modest decrease in RhoA activation in association with rictor gene-silencing may be significant in the bladder cancer cells." (PMID 24312263, 2013). "Our study indicates that ARHGEF12 promotes chemoresistance in bladder cancer cells by modulating RhoA/ROCK signaling, which subsequently activates the PI3K/AKT pathway." (PMID 41310897, 2025). "It was indeed revealed that the R200K mutation is a naturally occurring hotspot mutation in bladder cancer that causes transcriptional upregulation of YAP/TAZ and MRTF-A/B via a RHOGEF - RHOA GTPase cascade." (PMID 39966435, 2025). "High RhoA and RhoC expression is correlated with poor tumor differentiation, muscle invasion, and lymph node metastasis in bladder carcinoma." (PMID 31108958, 2019). "We showed that laminin stimulates Lu/BCAM to increase the adhesion of NIH-Lu and bladder cancer cells through RhoA/Rac1 signalling pathway." (PMID 28841878, 2017). "To explore the underlying molecular mechanisms, we treated bladder cancer cells with HA-1077 and then examined changes of the GTP-bound active form of RhoA and expression of its downstream effector ROCK." (PMID 24908363, 2014). "70-80% of the cells from both bladder cancer cell lines showed moderate to strong cytoplasmic staining by anti-RhoA antibody, and weak to moderate cytoplasmic staining by anti-ROCK-I and anti-ROCK-II antibodies." (PMID 24908363, 2014). "In our experiments with J82 bladder cancer cells, rictor gene-silencing substantially decreased Rac1 activation while having a more modest effect on RhoA." (PMID 24312263, 2013). "Moreover, RhoA activity was decreased in ZHX3-knockdown bladder cancer cells but was significantly increased in ZHX3-knockdown bladder cancer cells treated with siRGS2." (PMID 37627900, 2023). "Similarly, another study reported that the high-expression of RhoA and RhoC were associated not only with muscle invasion and LNM (P<0.001, P<0.05, respectively), but also with poorer survival in bladder cancer (P<0.0001)." (PMID 22860091, 2012). "RACGAP1-mediated activation of RhoA can enhance the activity of YAP1/TAZ, thereby assisting PLAGL2 in promoting the progression of bladder cancer." (PMID 38898473, 2024). "Considering the oncogenic role of RACGAP1 in the malignant behaviors of bladder cancer cells, we inferred that RACGAP1 exerts cancer-promoting functions via the upregulation of p-STAT3, active RhoA, and p-ERK1/2." (PMID 35013128, 2022). "Consistently, the overexpression of the RhoA protein marker has been reported in various cancers, including HCC and colon, testicular, breast, head and neck, lung and bladder cancers." (PMID 32731493, 2020). "Moreover, Pleomorphic adenoma gene like-2 (PLAGL2) facilitated bladder cancer progression via RACGAP1/RhoA GTPase/YAP1 signaling, and its proproliferative and prometastatic effects were negated by the RhoA inhibitor simvastatin." (PMID 39101139, 2024). "In this study, we found that cell movement is RAC1-dependent in bladder cancer, and RAC1 activity, but not RhoA and CDC42, is inhibited by RACGAP1, which is partially reversed following SHCBP1 ectopic expression." (PMID 35013128, 2022).
non-small cell lung carcinoma (21 papers, 2016 to 2025). A group of at least three distinct histological types of lung cancer, including non-small cell squamous cell carcinoma, adenocarcinoma, and large cell carcinoma. "Several recent studies have explored the functional importance of RhoA and other Ras GTPases, with RhoA hyperactivation having been linked to proliferation and chemoresistance in gastric, bladder, and non-small cell lung cancer." (PMID 34627383, 2021). "GAL3 knockdown effectively inhibited RhoA expression in hypoxic non-small cell lung cancer cells and GAL1 knockdown inhibited Ras expression in specific cell types." (PMID 41169985, 2025). "We previously found that Neferine inhibited the migration and invasion of non-small cell lung cancer through the RhoA/Rho pathway." (PMID 37446748, 2023). "FPPS can mediate the epithelial-mesenchymal transition (EMT) and invasion of TGF-β1-induced non-small cell lung cancer cells via RhoA/ROCK1 signaling pathway." (PMID 34486491, 2021). "We recently reported that a novel class of compounds (PCAIs), induced a decrease in the levels of RhoA in the NCI-H1299 non-small cell lung cancer cells to disrupt F-actin organization and abrogate cell migration." (PMID 29899821, 2018). "Furthermore, TNS1 drives the growth and metastasis of non-small-cell lung cancer (NSCLC) cells via the Akt/mTOR/RhoA pathway." (PMID 40906372, 2025). "Furthermore, farnesyl pyrophosphate synthase promoted TGF-β-induced EMT via RhoA activation in non-small-cell lung cancer cells." (PMID 31546735, 2019). "In non-small cell lung cancer cells, TGF-β signaling upregulated the expression of MRTF (through a RhoA/ROCK non-canonical mechanism), which interacted with NF-κB/p65 to promote PD-L1 expression through transcription." (PMID 35159327, 2022).
pulmonary fibrosis (21 papers, 2006 to 2025). Chronic progressive interstitial lung disorder characterized by the replacement of the lung tissue by connective tissue, leading to progressive dyspnea, respiratory failure, or right heart failure. "Attenuation of p190RhoGAP has been implicated as an additional mechanism for enhanced RhoA activity in settings of mechanical tension, such as in fibroblasts derived from patients with idiopathic pulmonary fibrosis." (PMID 35223831, 2022). "The results demonstrated that the activity of lung histone RhoA was significantly enhanced in the BLM group of a bleomycin-induced lung fibrosis model, and the intervention of GL-V9 was found to effectively inhibit the enhancement of RhoA activity." (PMID 40216763, 2025). "During the progression of pulmonary fibrosis, the reorganization of the actin cytoskeleton mediated by the ROS/RhoA-ROCK pathway induces myofibroblast transformation and collagen synthesis, ultimately influencing the outcome of lung fibrosis." (PMID 39512901, 2024). "Conclusively, JTE-013 has great anti-pulmonary fibrosis potential by regulating RHOA/YAP and mitochondrial fusion/fission." (PMID 37895915, 2023). "The etiology of idiopathic pulmonary fibrosis is unclear, but increased levels of TGFβ are an important contributor to fibrosis, and there is ample support for an influential role of RhoA in this disease and other kinds of fibrosis." (PMID 35223831, 2022). "RhoA is also involved in regulating myocardial and pulmonary fibrosis, and sustained activation of the RhoA pathway leads to inhibited differentiation of skeletal muscle stem cells." (PMID 33361519, 2020). "The authors also showed that cyclin D1 expression is deregulated in idiopathic pulmonary fibrosis through a RhoA-dependent mechanism that influences lung fibroblast proliferation." (PMID 22942703, 2012). "Tentatively, we provide evidence to support future exploitation of direct RhoA inhibition (using HMG CoA inhibitor agents) as a novel strategic option for fibroproliferative abrogation in lung fibrosis." (PMID 16776827, 2006). "Therefore, JTE-013 exhibits significant potential in reducing pulmonary fibrosis by modulating the RHOA/YAP pathways and mitochondrial fusion/fission." (PMID 37895915, 2023). "Thus, GL-V9 exerts its anti-pulmonary fibrosis effects by inhibiting RhoA activity." (PMID 40216763, 2025). "The reorganization of actin cytoskeleton through the ROS/RhoA-ROCK pathway mediates the toxic effects of fibroblast transdifferentiation and the synthesis of collagen in lung fibrosis." (PMID 37786441, 2023). "In this study, we demonstrated the potential of JTE-013 to regulate the RHOA/YAP pathway and mitochondrial dynamics in the context of pulmonary fibrosis." (PMID 37895915, 2023). "ECM stiffness and mechanical signaling (i.e., RhoA/ROCK, myocardin-related transcription factor-A [MRTF-A], and YAP/TAZ) promote pulmonary fibrosis via TRPV4-related signaling and others." (PMID 37518181, 2023). "Evidence demonstrated that substrate stiffness regulated the migratory and invasive ability of cells via RhoA/ROCK pathway and that enhanced RhoA activity is indicative of a variety of diseases (including IPF, Idiopathic pulmonary fibrosis)." (PMID 35309934, 2022). "In the study of lung diseases, NOX4/ROS can activate the RhoA/ROCK1 signal pathway, promote the migration of pulmonary fibroblasts and collagen synthesis, and aggravate pulmonary fibrosis." (PMID 34135982, 2021). "Recent studies have indicated that in pulmonary fibrosis, NOX4/ROS can activate the RhoA/ROCK signalling pathway, promote lung fibroblast migration and collagen synthesis, and enhance pulmonary fibrosis development." (PMID 32496208, 2020). "In lung fibrosis, NOX4/ROS is located upstream of the RhoA/ROCK1 signaling pathway, and the two molecules are oppositely located in renal fibrosis." (PMID 31130857, 2019).
pulmonary fibrosis (continued). "This interaction effectively inhibits the RhoA-ROCK signaling pathway, which is critical in preventing the activation of myofibroblasts and the M2 polarization of macrophages, leading to the mitigation of pulmonary fibrosis." (PMID 40216763, 2025). "Animal studies suggest that RhoA and ROCK inhibitors, as well as ROS scavengers, could be potential strategies for preventing and treating oxygen toxicity-induced pulmonary fibrosis." (PMID 39512901, 2024). "Snail1/RhoA/α-SMA pathway is a proven mechanism involved in fibroblast activation, and several studies have demonstrated that Snail1 participated in organ fibrosis, i.e., renal fibrosis, cardiac fibrosis, and lung fibrosis." (PMID 38615011, 2024). "In pulmonary fibrosis, NOX4/ROS is an upstream signalling pathway of RhoA/ROCK1." (PMID 32496208, 2020). "The small GTPase, RhoA, and its target protein, Rho-kinase (ROCK), may interact with other signaling pathways known to contribute to pulmonary fibrosis." (PMID 22942703, 2012). "In summary, we found that JTE-013 could regulate mitochondrial function by inhibiting the expression of RHOA/YAP signaling pathway proteins, mediate mitochondrial fusion/fission signaling, and regulate ROS production, thus attenuating the development of pulmonary fibrosis." (PMID 37895915, 2023). "Also the fact that membrane-bound ICAM-1 regulates the Src kinases activity, which controls the RhoA/ROCK/MLC2 signaling pathway, is in accordance with previous data suggesting a role for Src in fibroblast contractility and during kidney and lung fibrosis." (PMID 27901489, 2017).
pulmonary hypertension (21 papers, 2011 to 2025). Increased pressure within the pulmonary circulation due to lung or heart disorder. "ARHGEF12, also known as leukemia-associated Rho GEF (LARG), has been implicated in the progression of various diseases, including cancer, pulmonary arterial hypertension, and pathogenic thrombus formation, primarily through its role in RhoA activation and its effects on the actin cytoskeleton." (PMID 41306285, 2025). "The presence of CSS, including the RHOA gene, might suggest the presence of variants in this gene that contribute to resistance to pulmonary hypertension." (PMID 38773423, 2024). "Activation of RhoA and its downstream mediator Rho-associated kinase is implicated in the pathogenesis of pulmonary hypertension (PH) and inhibition of the RhoA/Rho-kinase may also contribute to the beneficial effects of established therapies, such as sildenafil." (PMID 21999923, 2011). "Interestingly, even if CDH has not been reported in patients affected by Ectodermal dysplasia with facial dysmorphism and acral, ocular, and brain anomalies, animal models of CDH have been shown to present altered pulmonary RhoA expression, which may be linked to pulmonary hypertension." (PMID 41153384, 2025). "Fasudil is a novel RhoA/Rho kinase (ROCK) inhibitor that has shown great potential in effectively treating pulmonary hypertension." (PMID 34959469, 2021). "Umbelliferone could ameliorate hypoxia-induced pulmonary hypertension by inhibiting RhoA/ROCK signaling pathway and autophagy." (PMID 39544928, 2024). "A serotonylation study in pulmonary hypertension in smooth muscle cells has shown RhoA protein to be significantly decreased at 24, 48, and 72 hours post 5HT stimulation, with decreased protein being attributed to the degradation feedback to eliminate activity." (PMID 33095824, 2020). "Evidence that the RhoA/ROK pathway contributes to the vasoconstrictor component of pulmonary hypertension is demonstrated by effects of ROK inhibitors to acutely reduce pulmonary arterial pressure in both chronically hypoxia rats and in the hypoxia/SU5416 rat model of angioproliferative PAH." (PMID 28666030, 2017). "Hypoxia has previously been reported to increase α-actin expression and RhoA dependent actin polymerization in the lung during the development of pulmonary hypertension and, in view of this, we examined the effect of the CREBαΔ mutation on the expression of smooth muscle α-actin." (PMID 24349008, 2013). "Similarly, activation of RhoA increased ASIC1a expression on the plasma membrane and enhanced store-operated Ca2+ entry in the pulmonary arterial smooth muscle cells, which might help improve our understanding of the vital role of RhoA in the pathogenesis of pulmonary hypertension." (PMID 33195276, 2020). "A total of 15 patients without pulmonary hypertension (non-PAH), 19 patients with PAH and 25 patients with CTEPH were studied by measuring conventional markers, GTP-related Rap1 levels, RhoA, RalA, Rac1 and Ras in the platelets." (PMID 36984870, 2023).
diabetic nephropathy (20 papers, 2013 to 2025). "A recent study showed that HSPA5 can also be involved in diabetic nephropathy by targeting RhoA and activating the PI3k/Akt pathway." (PMID 35935760, 2022). "Statins, which are best known for their lipid-lowering effects, also ameliorate the progression of diabetic nephropathy, and both effects have been attributed to inhibition of RhoA/ROCK." (PMID 30972066, 2019). "Conversely, several studies have shown that excessive RhoA activation is also detrimental in diabetic nephropathy and that its inhibition may offer therapeutic benefits." (PMID 41306285, 2025). "We questioned whether statins influence development of diabetic nephropathy through reactive oxygen species, RhoA and Akt/GSK3 pathway, known to be important in renal pathology." (PMID 27649495, 2016). "In studies of diabetic nephropathy pathogenesis, it is discovered that the disruption in expression and translocation of ZO-1 and occludin in glomerular endothelial cells could be stimulated by reactive oxygen species and RhoA/ROCK pathway." (PMID 37430272, 2023). "Thus, it is obvious the RhoA/ROCK pathway plays an important role in diabetic nephropathy." (PMID 28054559, 2017). "Likewise, RhoA deregulation appears to be involved in a progression of diabetic nephropathy." (PMID 24839453, 2014). "The regulation of this pathway is involved in the treatment of various diseases since abnormal RhoA/ROCK signaling results in the pathophysiology of a large number of disorders, including traumatic brain injury, osteoarthritis and diabetic nephropathy." (PMID 35188451, 2022). "Metformin reduces RhoA activity and activates AMPK, while Fasudil, a selective RhoA inhibitor used to treat diabetic nephropathy, improves insulin signaling and nephropathy by correcting glucose and lipid homeostasis in obese Zucker rats." (PMID 30972066, 2019). "Since podocytes rely on strongly regulated RhoA signaling to preserve their complex architecture—including foot processes and slit diaphragms—DLC1 upregulation may destabilize the glomerular filtration barrier and promote proteinuria in diabetic kidney disease." (PMID 41306285, 2025).